BCL9 (BCL9 transcription coactivator)
Diseases named in the same sentence as BCL9 in open-access papers (continued):
Sharing a sentence is not in itself a finding about the gene and the disease.
breast cancer (21 papers, 2007 to 2026). A primary or metastatic malignant neoplasm involving the breast. "Apparently, the complete loss of Bcl9/Bcl9L impairs survival of mammary tumor cells, while the disruption of the β-catenin-Bcl9/Bcl9L-Pygopus chain of adapters only affects the tumorigenic behavior of the tumor cells." (PMID 34545187, 2021). "Together these results indicate that the complete loss of Bcl9 and Bcl9L function in mammary tumor cells provokes their apoptotic death." (PMID 34545187, 2021). "In breast cancer, BCL9 has been identified as a prognostic biomarker for high-risk human ductal carcinoma in situ (DCIS)." (PMID 34545187, 2021). "According to recent publications, BCL9 is a specific breast cancer associated gene that contributes to the invasion and EMT of breast ductal carcinoma but not of other subtypes, thereby indicating its potential subtyping relevance." (PMID 31480430, 2019). "Our initial findings suggest that BCL9 expression and activity are important risk factors for breast cancer progression." (PMID 26384318, 2015). "In summary, the results showed that the methylation pattern of HOXD9, ZNF154, and BCL9 genes in peripheral blood leukocytes could be used as a potential biomarker for breast cancer risk assessment." (PMID 34452548, 2021). "Among the DNA methylation features, probes such as cg03441279 in BCL9 and cg12427162 in SFT2D2 have been associated with breast cancer prognosis." (PMID 40093058, 2025). "The results showed that in breast cancer patients, overexpression of RBBP5, TPR, and BCL9 was significantly associated with poor clinical outcomes (p<0.05)." (PMID 36835467, 2023). "Evidence shows its involvement in promoting mammary tumor growth and metastasis in mice as well as its activation in hepatocellular carcinoma under hypoxic conditions, both through BCL9/BCL9L and Wnt pathway activation." (PMID 37627176, 2023). "In summary the interaction of Bcl9/Bcl9L with Pygopus appears to play only a limited role in the regulation of breast cancer tumor progression." (PMID 34545187, 2021). "Analysis of the expression of Bcl9 and Bcl9L revealed that both proteins are highly expressed during mammary tumor progression in MMTV-PyMT transgenic mic." (PMID 34545187, 2021). "BCL9 amplification correlated with poor prognosis in breast cancer patients (cBioportal online tool)." (PMID 34545187, 2021). "To investigate the functional relevance of Bcl9 and Bcl9L during tumor progression and invasion, we genetically deleted both Bcl9 and Bcl9L genes in mammary tumor cells of MMTV-PyMT mice." (PMID 34545187, 2021). "The results suggest that in breast cancer Bcl9/9L-dependent Wnt/β-catenin signaling regulates genes promoting tumor cell growth and metastasis." (PMID 34545187, 2021). "Three novel DMRs located in promoter regions of HOXD9, ZNF154, and BCL9 genes were confirmed in the peripheral blood of breast cancer patients." (PMID 34452548, 2021). "Database mining indicated that BCL9 and only to a lesser extent BCL9L are found mutated in breast cancers of patients." (PMID 34545187, 2021). "A recent publication reported that BCL9 is a breast cancer-related gene that contributes to invasion and EMT in breast ductal carcinoma." (PMID 34452548, 2021). "To examine the relevance of Bcl9 and Bcl9L in tumor progression and invasion in breast cancer patients, we first analyzed the genetic alteration of both genes in breast cancer patient data (from TCGA-BRCA PanCancer Atlas data collection)." (PMID 34545187, 2021). "High expression of BCL9 is often observed in many malignant tumors, including colorectal cancer, liver cancer, and breast cancer and it contributes to tumor progression, recurrence, and metastasis." (PMID 33552975, 2020). "METABRIC database in cBioPortal, which includes 2,509 cases of breast cancer, showed significantly higher BCL9 mRNA expression in luminal A, B and basal-like breast cancers compared to other subtypes." (PMID 32352029, 2020).
breast cancer (continued). "Taken together, these results suggest that aberrant elevated expression of BCL9 in breast cancers is driven by BCL9 genomic amplification and/or promoter hypomethylation." (PMID 32352029, 2020). "The TCGA data were also analyzed for the expression of differentially expressed genes in breast cancers that showed BCL9 upregulation." (PMID 26384318, 2015). "A significantly higher proportion of basal like invasive breast cancers compared to luminal breast cancers showed BCL9 amplification." (PMID 26384318, 2015). "An IPA analysis on the differentially expressed genes showed Wnt/β-catenin pathway to show a significant upregulation in BCL9-high compared to BCL9-low breast cancers." (PMID 26384318, 2015). "The cancer genome atlas data were analyzed to assess the status of BCL9 gene alterations in breast cancers." (PMID 26384318, 2015). "For Breast cancer 6 genes had significant aCGH/expression correlation at a level of 0.05 in all 7 breast cancer data sets (BCL9, AZIN1, TAF2, YTHDF1, TTC13, FBXL20)." (PMID 25148247, 2014). "Interestingly, interfering with the β-catenin-Bcl9/Bcl9L-Pygo chain of adapters only partially impaired the transcriptional response of mammary tumor cells to Wnt3a and TGFβ treatments." (PMID 34545187, 2021). "Since B9/B9L double-homozygous mutants of HD2 were lethal, we crossed heterozygous Bcl9/Bcl9LΔHD2/fl mutant mice with MMTV-PyMT transgenic mice to induce mammary tumor formation and with MMTV-Cre mice to delete the floxed alleles in mammary tumors of Bcl9/Bcl9LΔHD2/fl mutant mice." (PMID 34545187, 2021). "Moreover, they also analyzed TCGA gene expression data reporting that the Wnt/β-catenin pathway is significantly upregulated in BCL9-high cancers compared to BCL9-low breast cancers." (PMID 33808143, 2021). "The hypothesis of a central role of BCL9 and Wnt signaling pathway may have distinct functional implications in the pathogenesis of ductal and lobular breast cancers." (PMID 33808143, 2021). "Since B9/B9L double-homozygous mutants of HD1 were lethal, we crossed heterozygous Bcl9/Bcl9LΔHD1/fl mutant mice with MMTV-PyMT transgenic mice to induce mammary tumor formation and with MMTV-Cre mice to delete the floxed allele in mammary tumors of Bcl9/Bcl9LΔHD1/fl mutant mice." (PMID 34545187, 2021). "BCL9 gene amplification appeared to be the most frequent genetic alteration in breast cancer with highest levels of amplifications in basal type and lowest in normal-type breast cancers." (PMID 34545187, 2021). "We next assessed whether a mutation of the N-terminal domain in β-catenin, which abrogated the interaction with both Bcl9 and Bcl9L on the side of β-catenin, recapitulated the effects of B9/B9L-ΔHD2 in breast cancer progression." (PMID 34545187, 2021). "It is noteworthy that targeting of BCL9 inhibits DCIS in both the cell line and animal model moreover, our data may emphasize the role of BCL9 in breast cancer development." (PMID 34452548, 2021). "Additionally, METABRIC revealed that a significantly higher proportion of basal (25.8%) and luminal A (24.9%) breast cancers exhibited BCL9 genomic amplification." (PMID 32352029, 2020). "In addition, analysis of The Cancer Genome Atlas (TCGA) database showed significantly lower DNA methylation in the BCL9 promoter region (transcription start site ±3 kB) of luminal A and B breast cancers compared to control tissues." (PMID 32352029, 2020). "In summary, increased expression of BCL9, as observed in a significant fraction of breast cancer patients, may predict DCIS with invasive potential." (PMID 32352029, 2020). "Analysis of the TCGA data showed BCL9 to be altered in 26 % of breast cancers." (PMID 26384318, 2015). "BCL9 is located on chromosome 1q21, a common amplified region in breast cancer." (PMID 26384318, 2015). "BCL9 was found at approximately equal levels in all breast cancer cell lines." (PMID 25149534, 2014).
breast cancer (continued). "Thus, Bcl9 and Bcl9L may promote mammary tumor growth and metastasis formation in MMTV-PyMT mice in a rather moderate manner and by fine-tuning the expression levels of direct and indirect Wnt target genes." (PMID 34545187, 2021). "Furthermore, rosemary extract (or carnosic acid) may provide a new therapeutic strategy for prevention of breast cancer by targeting BCL9." (PMID 32352029, 2020). "However, our results show that the low expression of RBBP5 and BCL9 is related to a better prognosis of breast cancer, which indicates that the abnormal Wnt pathway may also be inhibited by reducing the expression of RBBP5 and BCL9 in breast cancer, thus achieving better targeted therapy." (PMID 36835467, 2023). "A total of 1799 differentially methylated regions were identified, including ZNF154, BCL9, and HOXD9, in which significant methylation differences were confirmed in breast cancer patients through a quantitative real-time polymerase chain reaction." (PMID 34452548, 2021). "We thus were motivated to investigate the specific contribution of Bcl9 and Bcl9L to β-catenin-mediated Wnt signaling and as a consequence to tumor progression in the MMTV-PyMT transgenic mouse model of breast cancer." (PMID 34545187, 2021). "Deubiquitination of BCL9 reinforces the construction of β-catenin/BCL9/PYGO complex, which in turn activates promoters of Wnt target genes and facilitates breast cancer carcinogenesis." (PMID 34575114, 2021). "LG2 markers include 190 genes, among which are many oncogenes, (BCL2 (down, breast cancer poor prognosis marker), RAD51 (up), EGFR (up), RUNX3 (up), BCL9 (down) and VAV3 (down) and tumor suppressor gene NME1 (up)." (PMID 17683614, 2007). "For example, in CD4+ T-cells, BCL9 for B-cell acute lymphoblastic leukemia (B-ALL); GAS7 and PRDM16 for Acute myelogenous leukemia (AML); ESR1 for breast cancer; and GRIN2A for colorectal, lung, and gastric carcinoma were differentially methylated between PWH and PWoH." (PMID 38466776, 2024). "In contrast, the high gene amplification and expression of BCL9 observed in this patient data set did not reveal a significant correlation with disease outcome in any of the breast cancer subtypes." (PMID 34545187, 2021). "Another study on BCL9 in breast ductal carcinoma confirmed that its methylation status and expression pattern are definitely functionally related to the expression of ERBB2 and HER2 in breast cancers." (PMID 31480430, 2019). "However, the role of BCL9 in mammary gland biology and breast cancer has not been explored previously." (PMID 26384318, 2015). "However, to our knowledge, there are currently no data on the role of BCL9 in breast cancer progression." (PMID 26384318, 2015). "We decided to concentrate on one of the genes in the canonical Wnt signaling pathway, B cell lymphoma-9 (BCL9), because it was found to serve as a co-factor of β-catenin in early 2000, however, there were no previous studies on the role of BCL9 in breast cancer." (PMID 26384318, 2015). "Together, the results indicate that Bcl9/Bcl9L modulate but are not critically required for canonical Wnt signaling in its contribution to breast cancer growth and malignant progression, a notion consistent with the “just-right” hypothesis of Wnt-driven tumor progression." (PMID 34545187, 2021). "However BCL9 role in breast cancer had not been previously recognized." (PMID 26384318, 2015). "However, in breast cancer, where mutations in APC or β-catenin are not commonly reported, BCL9 overexpression may be a molecular mechanism contributing to aberrant Wnt activation and progression." (PMID 26384318, 2015). "The mechanism by which BCL9 is overexpressed in some cancers is not entirely understood, but cancer genome analysis via GISTIC reveals copy number alterations in 13 % of all breast cancer cases examined." (PMID 26384318, 2015).
breast cancer (continued). "Among them, BCL9 was proven to be closely related to DCs in breast cancer, while the TPR and RBBP5 were shown to be closely related to DCs, but there is a lack of further research on breast cancer." (PMID 36835467, 2023). "How BCL9 and BCL9L contribute to the breast cancer progression is not clear." (PMID 34545187, 2021). "In conclusion, the results show that Bcl9 and more prominently Bcl9L contribute to the initiation and maintenance of TGFβ-induced EMT and cell migration of cultured mammary tumor cells in vitro, but that they are not exclusive determinants of these TGFβ-induced processes." (PMID 34545187, 2021).
hepatocellular carcinoma (15 papers, 2017 to 2024). A malignant tumor that arises from hepatocytes. "HIF-1α can activate Wnt/β-catenin signaling via regulating BCL9 expression in hepatocellular carcinoma." (PMID 38031108, 2023). "Another mechanism is suggested by the observation that the expression of BCL9 can be induced by hypoxia in human hepatocellular carcinoma: BCL9 levels can also be stabilized by the deubiquitinase USP9X in a variety of cancer cell lines." (PMID 34545187, 2021). "MiR-3194-3p represses the stemness and EMT of hepatocellular carcinoma cells through targeting BCL9." (PMID 34516362, 2021). "In addition, these applications in other cancer types with survival related to BCL9, such as hepatocellular carcinoma, melanoma and triple negative breast cancer, need to be investigated." (PMID 38811552, 2024). "In hepatocellular carcinoma, the down-regulation of miR-1301 expression can up-regulate the expression of its target gene BCL9 and activate the Wnt/β-catenin signaling pathway, thereby inhibiting the migration, invasion, EMT, and angiogenesis of hepatocellular carcinoma." (PMID 35070996, 2021). "BCL9L overexpression is positively correlated with poor overall survival in hepatocellular carcinoma patients, and silencing BCL9L, but not BCL9, reduced Wnt signaling, and suppressed cell growth and induced apoptosis of Wnt-inactive hepatocellular carcinoma cells." (PMID 33436545, 2021).
multiple myeloma (15 papers, 2010 to 2023). "A treatment that targets mir-30-5p and inhibits BCL9 was shown to reduce tumor burden and metastatic potential in a human multiple myeloma cell xenograft model in mice, which affects the orthopedic diseases of mice irreversibly." (PMID 31827404, 2019). "BCL9 has been shown to play a critical role in progression of colorectal cancers and multiple myeloma by activation of Wnt oncogenic signaling." (PMID 26384318, 2015). "Finally, in multiple myeloma, an osteolytic disease, miR-30b-3p has a tumor suppressor role targeting the Wnt/b-Catenin/BCL9 Pathway." (PMID 33800656, 2021). "In multiple myeloma cells, re-expression of PCDH10 suppressed nuclear localization of β-catenin, activity of LEF/TCF, expression of the β-catenin transcriptional cofactor BCL9, and of AKT, whereas expression of GSK3β was increased." (PMID 35468745, 2022).
schizophrenia (10 papers, 2013 to 2025). A major psychotic disorder characterized by abnormalities in the perception or expression of reality. "A GWAS covering the Han Chinese population, including 5,772 controls and 4,187 schizophrenia patients, revealed multiple single nucleotide polymorphisms (SNPs) located in the BCL9 gene that are significantly associated with schizophrenia." (PMID 40792073, 2025). "BCL9 has emerged as a key genetic contributor to schizophrenia susceptibility through its regulation of the Wnt pathway." (PMID 40792073, 2025). "Among these, rs583583 showed the most significant association, further suggesting a potential role of BCL9 in schizophrenia susceptibility." (PMID 40792073, 2025). "Rare recurrent microdeletions at 1q21.1 were reported to be associated with schizophrenia, and the BCL9 gene at 1q21.1 was also a functional candidate gene for mental disorders." (PMID 35328011, 2022). "We found that CHD1L is a candidate for autism spectrum disorder (ASD) and attention deficit hyperactivity disorder (ADHD), whereas PRKAB2 and BCL9 have been associated to schizophrenia." (PMID 29922639, 2018). "This study demonstrated that common SNVs in the BCL9 gene confer risk of schizophrenia and may also be associated with bipolar disorder and major depressive disorder in the Chinese Han population." (PMID 35328011, 2022). "Furthermore, common variants in the BCL9 gene are associated with schizophrenia, bipolar disorder, and major depressive disorder." (PMID 23825557, 2013). "BCL9 (OMIM: 602597), located at 1q21.1, is a schizophrenia susceptibility gene that encodes a nuclear retention factor for β-catenin." (PMID 40792073, 2025). "BCL9 itself is a candidate for schizophrenia and interacts as well with genes important for language development and evolution." (PMID 29922639, 2018). "Additional GWAS and meta-analyses provide further evidence supporting these findings, suggesting that BCL9 is implicated in the negative symptoms of schizophrenia and designating it as one of the most prominent high-risk candidate genes for the disorder." (PMID 40792073, 2025). "Their results indicate that BCL9 is unlikely to harbor a common genetic variant that contributes to the increased risk of schizophrenia in the Japanese population." (PMID 40792073, 2025). "The BCL9 gene is proposed as a candidate gene for schizophrenia." (PMID 37692779, 2023). "A recent study reported that SNV rs583583 in the BCL9 gene is associated with negative symptoms of schizophrenia, as measured by the Positive and Negative Syndrome Scale (PANSS), in the Caucasian population." (PMID 35328011, 2022). "A recent study reported that a single nucleotide polyphormism (SNP) within BCL9 (rs583583) is associated with negative symptoms of Schizophrenia, as measured by the Positive and Negative Syndrome Scale (PANSS), in the Caucasian population." (PMID 26494551, 2015). "B-cell CLL/lymphoma 9 (BCL9) is located within the schizophrenia (SCZ) suspected locus chr1q21.1." (PMID 26494551, 2015). "Moreover, specific SNPs within the BCL9 gene have been significantly associated with the negative symptoms of schizophrenia, further supporting its potential as a risk candidate gene." (PMID 40792073, 2025). "Additionally, another GWAS analyzing data from 1,774 European and American schizophrenia patients and 2,726 controls identified three SNPs in the BCL9 strongly linked to negative symptoms of schizophrenia." (PMID 40792073, 2025).